EGR2 (early growth response 2)
Diseases named in the same sentence as EGR2 in open-access papers (continued):
Sharing a sentence is not in itself a finding about the gene and the disease.
viral infection (continued). "The lack of Tfh cells was not due to a failure to activate EGR2/3-deficient CD4 T cells because EGR2/3-deficient CD4 T cells did not have defects in activation marker expression, as indicated by CD44high cell frequency, or effector cytokine expression in response to viral infection." (PMID 25979336, 2015). "Egr2 negative PD-1high MP CD4 T cells are impaired in homeostatic proliferation and adaptive responses against viral infection but display inflammatory responses to innate stimulation such as IL-12." (PMID 32709717, 2020). "In the absence of EGR2 and -3, the expression of BCL6 in Tfh cells is defective, leading to impaired differentiation of Tfh cells, resulting in a failure to form GCs following virus infection and defects in production of antiviral antibodies." (PMID 25979336, 2015).
autoimmune disease (11 papers, 2017 to 2025). A disorder resulting from loss of function or tissue destruction of an organ or multiple organs, arising from humoral or cellular immune responses of the individual to their own tissue constituents. "Variants in EGR2 are associated with the autoimmune diseases, systemic lupus erythematosus, and celiac disease." (PMID 37080976, 2023). "PD-1high memory CD4 T cells are pathogenic in autoimmune disease; here they show their expression of Egr2 is defective in rheumatoid arthritis and Egr2 & 3 control their inflammation and homeostasis." (PMID 32709717, 2020). "For instance, Egr2 deficiency in T cells causes lupus-like autoimmune disease." (PMID 40693464, 2025). "In the current study, we found that Egr2 deletion in B6/lpr mice significantly reduced the expression of DNA methylation–sensitive Dlk1-Dio3 miRNAs, which are upregulated and implicated in the pathogenesis of autoimmune diseases such as lupus and MS." (PMID 38153351, 2023). "Conditional deletion of EGR2 in CD2+ lymphocytes in non-autoimmune B6 mice led to a break in immune tolerance and induction of a T cell-driven, lupus-like autoimmune disease in EGR2-/-B6 mice." (PMID 35784356, 2022). "It has been reported that EGR2 deletion in B6 mice induced lupus-like autoimmune disease in aged mice with increased levels of anti-dsDNA autoantibodies and total IgG in serum." (PMID 35784356, 2022). "Accumulation of CD44+ effector T cells and heightened production of IFNγ and IL-17 also play a major role in the development of lupus-like autoimmune disease in EGR2-/-B6 mice." (PMID 35784356, 2022). "Elevated EGR2 expression has also been noted in biopsy specimens of skin and lungs from patients with systemic sclerosis, an autoimmune disease that has overlapping symptoms with lupus." (PMID 35784356, 2022). "Despite high PD-1 expression, Egr2/3−/− MP CD4 T cells are highly inflammatory leading to the development of autoimmune disease." (PMID 32709717, 2020). "These novel findings shed light on the understanding of PD-L1-mediated immune tolerance and suggest the potential therapeutic targeting of Klf1 and Egr2 in the treatment of autoimmune diseases and malignancies." (PMID 29728568, 2018). "In this review, we focus on the role of Egr2 in Tregs and also discuss its therapeutic potential for the treatment of autoimmune diseases." (PMID 29535721, 2018). "Recent genome-wide association studies (GWAS) have identified new genetic links between Egr2 and human autoimmune diseases." (PMID 29535721, 2018). "Defects in Egr2 and 3 lead to the development of autoimmune disease with high levels of IFN-γ–producing CD4 T cells." (PMID 28455436, 2017). "Moreover, elevated EGR2 has been noted in the murine scleroderma and also in skin and lung biopsy specimens from patients with systemic sclerosis, an autoimmune disease that has overlapping symptoms with lupus." (PMID 32646370, 2020). "The increased proportion of CD5high cells among Egr2/3−/− MP CD4 T cells, and auto-reactive T cells and autoimmune disease in CD2-Egr2/3−/− mice suggests that these enriched clones may have high affinity for self-antigen." (PMID 32709717, 2020). "Previous studies have reported that deletion of the transcription factor, early growth response protein 2 (EGR2), in normal C57BL/6 (B6) resulted in the development of lupus-like autoimmune disease." (PMID 35784356, 2022). "In addition, due to the overlapping role of EGR2 and EGR3, deletion of both EGR2 and EGR3 genes is necessary for the development of severe lupus-like autoimmune disease in B6 mice." (PMID 35784356, 2022). "Our findings indicate that Klf1 and Egr2 are modulators of PD-L1-mediated immune suppression in CD4+ T cells and might provide new insights into therapeutic targets for autoimmune diseases and malignancies." (PMID 29728568, 2018).
autoimmune disease (continued). "In this study, to further clarify the role of EGR2 in autoinflammation condition versus normal physiological condition, we derived conditional EGR2 knockout mice in both B6/lpr (a lymphoproliferative, systemic lupus erythematosus (SLE)-like autoimmune disease model) and normal B6 genetic background." (PMID 35784356, 2022).
Autoimmunity (11 papers, 2010 to 2023). The occurrence of an immune reaction against the organism's own cells or tissues. "The importance of Egr2 and 3 in controlling the development of autoimmunity was discovered in aged CD2-specific Egr2-deficient mice and in CD2-specific Egr2- and Egr3-deficient mice." (PMID 28487311, 2017). "Whether and how the upregulated EGR2 contributes to CD4+ T cell-mediated inflammation of autoimmunity in lupus needs to be further investigated, particularly in vivo in lupus mice with EGR2 deficiency." (PMID 32646370, 2020). "EGR2 has been linked to autoimmunity and various immune responses related to cancer." (PMID 29632393, 2018). "It is possible that EGR2 regulates autoimmunity in lupus mice via the regulation of Dlk1-Dio3 miRNAs." (PMID 38153351, 2023). "Although the role of methylation in EGR2-mediated regulation of Dlk1-Dio3 miRNAs is not readily apparent, these are the first data to show that in lupus, Egr2 regulates Dlk1-Dio3 miRNAs, which target major signaling pathways in autoimmunity." (PMID 38153351, 2023). "The critical roles of EGR2 in regulating T cell development and activation, adaptive immune response, inflammatory cytokine production, and autoimmunity have been widely investigated recently and well-acknowledged." (PMID 38153351, 2023). "The critical and complex roles of EGR2 in immunity and autoimmunity have now been extensively studied." (PMID 38153351, 2023). "EGR2 acts as a key regulator for systemic autoimmunity by regulating cytokine production and cell proliferation." (PMID 35140805, 2022). "We have also previously observed that Egr2−/− MP CD4 T cells in old CD2- Egr2−/− mice, which are also prone to develop autoimmunity, have increased homeostatic proliferation." (PMID 32709717, 2020). "This suggests the potential possibility to target Egr2 in macrophages to inhibit their activation during inflammatory diseases such as autoimmunity." (PMID 30443252, 2018). "Forced expression of EGR2 in naïve T cells converts them into LAG3 expressing and IL-10 secreting regulatory cells while EGR2 deficiency results in lupus-like autoimmunity, as well as increased STAT3 phosphorylation and IL-17 secretion." (PMID 25880134, 2015). "Nevertheless, in other autoimmune conditions, especially rheumatic diseases, EGR2 may have a different role." (PMID 32646370, 2020). "In addition, EGR2 polymorphisms influence SLE susceptibility in humans, suggesting that Ly108 regulates autoimmunity through EGR2 induction." (PMID 33114612, 2020). "Moreover, other than its suppressive role on T cell-mediated inflammation, EGR2 has also been shown to control autoimmunity by regulating the function of FoxP3 independent CD4+CD25−LAG3+ Treg cells." (PMID 32646370, 2020). "The current understanding of the role of EGR2 in immunity and autoimmunity is primarily based on data derived from genetically modified B6 mice that may not fully capture the function of EGR2 in diverse pathological contexts." (PMID 38153351, 2023).
lupus (11 papers, 2015 to 2025). "Nevertheless, a candidate gene promoter polymorphism analysis indicated that increased EGR2 gene expression is linked with lupus susceptibility in humans." (PMID 35784356, 2022). "EGR2 has also been associated with susceptibility to Crohn's disease, Behcet's disease, and systemic lupus erythematosus." (PMID 30915103, 2019). "Conversely, increased EGR2 gene expression is suggested to link with high risk of human lupus." (PMID 32646370, 2020). "Increased EGR2 expression is suggested to link with lupus susceptibility in humans." (PMID 32646370, 2020). "Candidate gene association analysis revealed that a regulatory polymorphism in the EGR2 gene was associated with susceptibility to both rheumatoid arthritis (RA) and lupus, and that increased EGR2 expression may contribute to lupus pathogenesis." (PMID 32646370, 2020). "Recent studies have shown an association of the Egr2 gene with the occurrence of lupus in mice." (PMID 29535721, 2018). "Another group reported that Egr2-deficient mice develop lupus-like autoimmune disease." (PMID 30071700, 2018). "We previously verified that polymorphisms in EGR2 are associated with susceptibility to SLE, and that Egr2 is characteristically expressed in LAG3+ Tregs, which have the potential to ameliorate lupus pathology." (PMID 30071700, 2018). "In this study, we reported that Egr2 deletion significantly reduced maternally expressed Dlk1-Dio3 miRNAs, suggesting that EGR2 plays an important role in the upregulation of Dlk1-Dio3 miRNAs in murine lupus CD4+ T cells." (PMID 38153351, 2023). "To test the potential epigenetic regulatory role of EGR2 in lupus CD4+ T cells, we evaluated the expression of selected methylation-sensitive Dlk1-Dio3 miRNAs, which are highly upregulated in lupus (e.g., miR-127, miR-154, miR-300, miR-279, and miR-433)." (PMID 38153351, 2023). "We recently reported a significant upregulation of EGR2 expression in both human lupus peripheral blood mononuclear cells (PBMCs) and murine lupus T cells." (PMID 35784356, 2022). "Together, our data demonstrated a significant increase of EGR2 expression in CD4+ T cells of murine lupus cells when compared to their respective controls." (PMID 32646370, 2020). "We further demonstrated that EGR2 plays a differential role in a lupus context since it positively regulated Th1 differentiation and IFNγ production in CD4+ T cells from MRL-lpr lupus mice." (PMID 32646370, 2020). "In normal C57BL/6 (B6) mice, deletion of EGR2 in lymphocytes results in the development of lupus-like systemic autoimmune disease, which implies indirectly an autoimmune protective role of EGR2." (PMID 32646370, 2020). "We found that EGR2 mRNA expression was significantly higher in human lupus PBMCs than healthy controls." (PMID 32646370, 2020). "We also analyzed the expression of EGR2 in different splenic cell subsets of a different murine lupus strain, B6.sle123 mice at resting state and following anti-CD3 and anti-CD28 stimulation." (PMID 32646370, 2020). "Together, our data suggested that EGR2 expresses at a low level in the resting T and B lymphocytes and that anti-CD3 and anti-CD28 stimulation significantly induces EGR2 expression in splenic T and B lymphocytes in both control and lupus mice." (PMID 32646370, 2020). "Our in vitro data suggest a positive role of EGR2 in the regulation of Th1 differentiation and IFNγ production in lupus effector CD4+ T cells." (PMID 32646370, 2020). "In the present studies we sought to clarify the expression and inflammation regulatory role of EGR2 in murine lupus T cells directly." (PMID 32646370, 2020). "By performing intracellular flow cytometry analysis, we found that EGR2 protein expression was significantly increased in resting lupus (either MRL-lpr or B6.sle123) CD4+ T cells when compared to CD4+ T cells from their respective non-autoimmune controls." (PMID 32646370, 2020).
lupus (continued). "To further investigate the role of EGR2 in lupus, we assessed the EGR2 expression in different splenic lymphocyte subsets in the MRL-lpr and B6.sle123 models as these two models have different genetic contributions in the disease pathogenesis." (PMID 32646370, 2020). "By utilizing MRL-lpr lupus model, we therefore investigated the role of EGR2 in the regulation of Th1 differentiation and Th1 cytokine IFNγ in the context of lupus." (PMID 32646370, 2020). "Together, our data revealed a common upregulation of EGR2 mRNA expression in human lupus and in different murine lupus models." (PMID 32646370, 2020). "It is possible that anti-CD3 and anti-CD28 activated T cells contributed to the increased EGR2 expression in B cells from lupus mice MRL-lpr mice either through the release of cytokines or co-stimulatory signals." (PMID 32646370, 2020). "An earlier study has reported that EGR2 was upregulated in the DNT cells of MRL-lpr (Faslpr mutation) and C3H-gld/gld (Faslgld mutation) lupus mice and bind to Fas ligand regulatory element (FLRE) to upregulate expression of Fas ligand (FasL)." (PMID 32646370, 2020). "To understand further the function of elevated EGR2 in lupus CD4+ T cells, we inhibited EGR2 with a specific siRNA in vitro in splenocytes from MRL-lpr and control MRL mice at 15 weeks-of-age." (PMID 32646370, 2020). "We therefore performed RT-qPCR analysis to compare EGR2 expression in peripheral blood mononuclear cells (PBMCs) from human lupus patients and healthy controls." (PMID 32646370, 2020). "The association between Egr2 and autoantibody-mediated systemic autoimmunity suggested a linkage between Egr2-expressing LAG3+ Tregs and the control of lupus activity." (PMID 29535721, 2018). "EGRs play an important role in the development of systemic autoimmune diseases, and the deficiency of EGR2 and EGR3, in particular, are related to the development of chronic inflammatory diseases, such as lupus, in murine models." (PMID 30319432, 2018). "However, increased EGR2 expression has been noted in human and murine lupus, which challenges the notion of the autoimmune suppressive role of EGR2 in B6 mice." (PMID 35784356, 2022). "We have shown that EGR2, a negative regulator of T cell activation, was increased in lupus cells." (PMID 35784356, 2022). "Therefore, to clarify the role of EGR2 in lupus, it is essential to investigate further the expression and function of EGR2 in the lupus setting." (PMID 32646370, 2020). "We next investigated whether EGR2 mRNA expression was upregulated in purified splenic CD4+ T cells from MRL-lpr mice as well as the other two different murine lupus stains B6.MRL-Faslpr/J (B6-lpr) and B6.NZMSle1/Sle2/Sle3 (B6.sle123) mice at diseased stage." (PMID 32646370, 2020). "Overall, our studies demonstrated that EGR2 is significantly upregulated in human and murine lupus." (PMID 32646370, 2020). "In our studies, we showed EGR2 expression is upregulated in human and murine lupus." (PMID 32646370, 2020). "The increase of EGR2 in CD4+ T cells may reflect the higher rate of activated CD4+ T cells (CD44+CD4+) in lupus mice." (PMID 32646370, 2020). "We performed RT-qPCR analysis and found a significant increase of EGR2 mRNA expression in human lupus PBMCs and in CD4+ T cells from three different murine lupus models including MRL-lpr, B6-lpr, and B6.sle123 mice at diseased stage when compared to age-matched control MRL or B6 mice." (PMID 32646370, 2020). "EGR2 expression was significantly increased in MRL-lpr mice at an age when lupus is manifested." (PMID 32646370, 2020). "The increase of EGR2 in lupus T cells might be a consequence of an inflammatory milieu with heightened T cell activation (CD44+CD4+) following lupus development." (PMID 32646370, 2020).
lupus (continued). "Although further experiments are needed to elucidate the role of EGR2 in the regulation of immune cell development and function in vivo in lupus, our data suggests that EGR2 may function differentially in specific autoimmune lupus context when compared to its role in physiological context." (PMID 32646370, 2020). "In our studies, we analyzed and compared the expression of EGR2 in resting and activated CD4+ T, CD8+ T, B cells of lupus and control mice." (PMID 32646370, 2020). "To understand the role of increased EGR2 in the context of lupus CD4+ T cells, we transfected splenocytes from MRL and MRL-lpr mice at 14–15 weeks-of age with specific EGR2 Dicer substrate siRNA (DsiRNA) to block EGR2 expression." (PMID 32646370, 2020). "Increased EGR2 expression, rather than decreased EGR2 expression, has been identified in human patients with lupus or systemic sclerosis and the murine models of these two diseases." (PMID 35784356, 2022). "Together, our data suggest that EGR2 positively regulates IFNγ production in MRL-lpr lupus CD4+ T cells, but not in control MRL CD4+ T cells." (PMID 32646370, 2020). "While EGR2+ Fas+ LAG3+ Tregs were able to suppress lupus development in MRL-lpr mice, neither EGR2 or Fas deficient LAG3+ Tregs had autoimmune suppressive role." (PMID 32646370, 2020). "Accordingly, in this study, we analyzed the expression of EGR2 in human lupus patients and in three different murine lupus models and detailed further the role EGR2 plays in the regulation of CD4+ T cell response and Th1 differentiation in lupus-prone mice." (PMID 32646370, 2020). "T cell-specific Egr2 conditional knockout (CKO) mice develop progressive lupus-like autoimmunity with no impact on the development of Foxp3-dependent CD25+ Tregs." (PMID 29535721, 2018). "The results of the present study demonstrated that LAG3+ Treg suppress thedevelopment of GCB andTFH, antibody production and disease progression in lupus-proneMRL/lpr mice.TGF-β3, which isproduced by LAG3+Treg in Egr2- and Fas-dependent manners, plays a criticalrole in suppressing humoral immunity." (PMID 25695838, 2015). "However, there is so far no comprehensive investigation of EGR2 expression and function directly in human lupus and/or in murine models of lupus." (PMID 32646370, 2020). "We found that EGR2 mRNA expression levels were significantly upregulated in purified splenic CD4+ T cells from diseased MRL-lpr (14–15 weeks-of-age), B6-lpr (18 weeks-of-age) and B6.sle123 (27–32 weeks of age) lupus mice when compared to their respective controls (MRL and B6 mice)." (PMID 32646370, 2020). "Importantly, we have shown that EGR2 is critical for Th1 differentiation and that inhibition of EGR2 in vitro suppresses IFNγ production only in MRL-lpr lupus CD4+ T cells, but not control MRL CD4+ T cells." (PMID 32646370, 2020). "We found that EGR2 inhibition significantly reduced IFNγ production in PMA and ionomycin activated MRL-lpr lupus CD4+ T cells, but not control MRL CD4+ T cells." (PMID 32646370, 2020). "We performed an intracellular flow cytometry assay to quantify EGR2 expressing cells and EGR2 protein expression intensity (determined by Median Fluorescence Intensity, MFI) in gated splenic CD4+ T cells of MRL-lpr and B6.sle123 lupus mice and non-autoimmune controls (MRL and B6)." (PMID 32646370, 2020).